GALE (UDP-galactose-4-epimerase)
Description:
Catalyzes two distinct but analogous reactions: the reversible epimerization of UDP-glucose to UDP-galactose and the reversible epimerization of UDP-N-acetylglucosamine to UDP-N-acetylgalactosamine. The reaction with UDP-Gal plays a critical role in the Leloir pathway of galactose catabolism in which galactose is converted to the glycolytic intermediate glucose 6-phosphate. It contributes to the catabolism of dietary galactose and enables the endogenous biosynthesis of both UDP-Gal and UDP-GalNAc when exogenous sources are limited. Both UDP-sugar interconversions are important in the synthesis of glycoproteins and glycolipids.
Synonyms: SDR1E1; THC13
Tractability: Small molecule: a structure with a bound ligand is known; it has a high-quality binding pocket; it belongs to a druggable protein family. PROTAC: ubiquitination databases record sites on it; its protein half-life has been measured; a small molecule that binds it is known.
Target class: Isomerase; Enzyme
Gene: Protein-coding gene on chromosome 1 (23,795,599 to 23,800,781, reverse strand). Ensembl gene ENSG00000117308.
Subcellular location (Human Protein Atlas): Cytosol; Golgi apparatus
Pathways (Reactome):
Disease: Defective GALE causes EDG
Metabolism: Galactose catabolism
Gene Ontology:
Molecular function: identical protein binding; protein homodimerization activity; UDP-glucose 4-epimerase activity; UDP-N-acetylglucosamine 4-epimerase activity
Biological process: galactose catabolic process; galactose catabolic process via UDP-galactose, Leloir pathway; galactose metabolic process
Cellular component: cytosol
Genetic constraint (gnomAD): Loss-of-function variants: 32 observed, 46.47 expected, observed/expected ratio (o/e) 0.69, 90% interval 0.52 to 0.93. The upper end of that interval is the gene's LOEUF score, 0.93, which puts it in group 3 of 6, group 1 being the genes least tolerant of losing a copy. Missense variants: 423 observed, 475.65 expected, observed/expected ratio (o/e) 0.89, 90% interval 0.82 to 0.96. Synonymous variants: 182 observed, 193.32 expected, observed/expected ratio (o/e) 0.94, 90% interval 0.83 to 1.07.
Gene-disease validity (ClinGen):
ClinGen rates the evidence that GALE causes each of these diseases.
galactose epimerase deficiency (autosomal recessive): Definitive. Galactose epimerase deficiency is a very rare, moderate to severe form of galactosemia characterized by moderate to severe signs of impaired galactose metabolism.
Homologues: Orthologues: chimpanzee GALE (99% identical), guinea pig GALE (93% identical), dog GALE (93% identical), mouse Gale (93% identical), rat Gale (93% identical), rabbit GALE (91% identical), macaque GALE (79% identical), pig GALE (78% identical), tropical clawed frog gale (74% identical), zebrafish gale (72% identical), Caenorhabditis elegans gale-1 (56% identical). Paralogues in human: SDR42E1 (23% identical), SDR42E2 (22% identical), HSD3B2 (22% identical), NSDHL (22% identical), HSD3B1 (21% identical), HSD3B7 (21% identical), TGDS (20% identical), UXS1 (20% identical), GMDS (18% identical), GFUS (15% identical).